TPM2 (tropomyosin 2)
Description:
Binds to actin filaments in muscle and non-muscle cells. Plays a central role, in association with the troponin complex, in the calcium dependent regulation of vertebrate striated muscle contraction. Smooth muscle contraction is regulated by interaction with caldesmon. In non-muscle cells is implicated in stabilizing cytoskeleton actin filaments. The non-muscle isoform may have a role in agonist-mediated receptor internalization.
Synonyms: TMSB; DA1; NEM4; AMCD1; CMYO23; CMYP23; DA2B; DA2B4; HEL-S-273
Tractability: PROTAC: ubiquitination databases record sites on it; its protein half-life has been measured.
Gene: Protein-coding gene on chromosome 9 (35,681,992 to 35,690,056, reverse strand). Ensembl gene ENSG00000198467.
Subcellular location: Cytoplasm, cytoskeleton
Pathways (Reactome):
Muscle contraction: Smooth Muscle Contraction; Striated Muscle Contraction
Gene Ontology:
Molecular function: actin binding; protein binding; actin filament binding; identical protein binding; protein heterodimerization activity; protein homodimerization activity; structural constituent of muscle
Biological process: regulation of ATP-dependent activity; actin filament organization; muscle contraction
Cellular component: actin cytoskeleton; actin filament; cytosol; muscle thin filament tropomyosin; cytoskeleton
Genetic constraint (gnomAD): Loss-of-function variants: 26 observed, 41.44 expected, observed/expected ratio (o/e) 0.63, 90% interval 0.46 to 0.87. The upper end of that interval is the gene's LOEUF score, 0.87, which puts it in group 3 of 6, group 1 being the genes least tolerant of losing a copy. Missense variants: 187 observed, 358.34 expected, observed/expected ratio (o/e) 0.52, 90% interval 0.46 to 0.59. Synonymous variants: 143 observed, 146.11 expected, observed/expected ratio (o/e) 0.98, 90% interval 0.85 to 1.12.
Gene-disease validity (ClinGen):
ClinGen rates the evidence that TPM2 causes each of these diseases.
TPM2-related myopathy (autosomal dominant): Definitive. A congenital myopathy of the musculoskeletal system that covers a wide spectrum of phenotypes and is caused by pathogenic variants in the skeletal muscle beta-Tropomyosin gene.
Homologues: Orthologues: chimpanzee TPM2 (100% identical), mouse Tpm2 (99% identical), pig TPM2 (99% identical), rat Tpm2 (99% identical), guinea pig TPM2 (94% identical), dog TPM2 (92% identical), macaque TPM2 (87% identical), tropical clawed frog tpm2 (76% identical), rabbit TPM2 (74% identical), Drosophila melanogaster Tm1 (54% identical), Caenorhabditis elegans lev-11 (51% identical), Drosophila melanogaster Tm2 (48% identical). Paralogues in human: TPM3 (86% identical), TPM1 (86% identical), TPM4 (65% identical).
Diseases named in the same sentence as TPM2 in open-access papers:
TPM2 is named in the same sentence as 96 diseases in open-access papers, as found by Europe PMC text mining. Sharing a sentence is not in itself a finding about the gene and the disease. The quoted sentences say what the papers report.
congenital myopathy (17 papers, 2012 to 2026). "TPM2 mutations are associated with various congenital myopathies, including nemaline myopathy, cap myopathy, and distal arthrogryposis, with underlying mechanisms involving calcium sensitivity abnormalities and sarcomere structural disruption." (PMID 40504789, 2025). "Genetic mutations in TPM1 are associated with cardiac hypertrophy, while genetic mutations in TPM2 were previously reported in patients with congenital myopathy." (PMID 36631981, 2023). "Mutations in the TPM2 gene encoding isoform Tpm2.2 are linked to distal arthrogryposis and congenital myopathy—skeletal muscle diseases characterized by hyper- and hypocontractile phenotypes, respectively." (PMID 33919826, 2021). "The present study therefore was undertaken to determine the molecular mechanisms of the congenital myopathy caused by one of the mutations in TPM2, leading to Gln147Pro (Q147P) substitution of Tpm2.2." (PMID 33066566, 2020). "Currently, HGMD (Professional 2018.1) shows that 35 disease-causing mutations within TPM2 cause 11 different myopathic conditions including nemaline myopathy, congenital myopathy, DA2B, DA1 and Cap disease." (PMID 30285720, 2018). "To conclude, our study documents the phenotype associated with a new heterozygous c.374+2T>C mutation within the TPM2 gene segregating with an unspecified congenital myopathy accompanied by facial dysmorphism and arthrogryposis." (PMID 27726070, 2017). "In this study we document a patient with a severe form of unspecified congenital myopathy, with arthrogryposis and facial dysmorphic features, in whom a new splice-site mutation within the TPM2 gene was found." (PMID 27726070, 2017). "Only two splice-site mutations within the TPM2 gene have been reported to date in patients with congenital myopathy." (PMID 27726070, 2017). "To date, only two splice-site mutations within the TPM2 gene have been shown to be causative for congenital myopathies." (PMID 27726070, 2017). "Among 27 TPM2 mutations reported to date in congenital myopathies, only two, i.e., c.240+2T>C and c.240+5G>A, are splice-site mutations." (PMID 27726070, 2017). "Certain mutations in TPM2 have been associated with congenital myopathies and may lead to muscle function abnormalities in offspring through inheritance." (PMID 40723322, 2025). "Finally, in agreement with previous studies, axial muscles and in particular long thoracic muscles in TPM2-mutated patients were predominantly involved in the adult congenital myopathy patients studied with our protocol and, together with subscapularis, also in AMD." (PMID 24932477, 2014). "While research on TPM2 has largely focused on muscle diseases (such as congenital myopathies) and cancer, its relevance to reproduction has gradually gained attention." (PMID 40723322, 2025). "Persons with distal forms of congenital myopathy had either homozygous missense, dominant, or de novo mosaic large deletions in NEB, and those with unspecified forms had dominant TPM2 variants." (PMID 38037113, 2023). "Mutations of TPM2 and TPM3 (tropomyosin 3) have been reported to cause various congenital myopathies, such as CAP myopathy, Nemaline myopathy types 1 and 4, and congenital myopathies with fiber-type disproportion." (PMID 34768447, 2021). "Recently, the second case of recessively inherited TPM2-related Escobar variant of MPS and congenital myopathy in a patient from a consanguineous family was described." (PMID 35052370, 2021). "Mutations in TPM2 and TPM3 are linked to congenital myopathies (CM) and distal arthrogryposis (DA), clinically and histologically variable disorders of skeletal muscle." (PMID 33919826, 2021). "The mutations in TPM2 and TPM3 genes lead to congenital myopathies—clinically and genetically heterogeneous muscle disorders that usually manifest at birth by muscle weakness and hypotension, slowly progressing over time." (PMID 33066566, 2020).
congenital myopathy (continued). "This includes mutations in genes encoding β-TM and γ-TM isoforms (TPM2 and TPM3) in association with congenital myopathies with a range of clinical and morphological phenotypes." (PMID 23273262, 2012). "Clarkson found that TPM2, actin, and troponin are mainly related to congenital myopathy." (PMID 31487691, 2019). "Two TPM2 mutations, i.e., c.349G>A, p.Glu117Lys and, c.364G>A; p.Glu122Lys, were identified in an unspecified congenital myopathy, diagnosed in the patients without specific structural alterations in the muscle biopsy specimen." (PMID 27726070, 2017). "While the majority of TPM2 gene mutations are causative for nemaline myopathy, cap disease or distal arthrogryposis, some mutations in this gene have been found to be associated with non-specific congenital myopathy." (PMID 27726070, 2017). "Using ML disease mapping, there were three further significant enrichments in TPM2-related diseases in the monocytic SDEG list, resulting from spaceflight effects, namely, distal arthrogryposis, congenital myopathy, and articular rigidity (FDR < 0.001)." (PMID 41481712, 2026). "Using the whole exome sequencing (WES) approach we were able to identify a novel heterozygous splice-site mutation within the TPM2 gene, showing the utility of WES in molecular diagnostics of congenital myopathies without recognizable morphological hallmarks." (PMID 27726070, 2017).
nemaline myopathy (16 papers, 2010 to 2026). Nemaline myopathy (NM) encompasses a large spectrum of myopathies characterized by hypotonia, weakness and depressed or absent deep tendon reflexes, with pathologic evidence of nemaline bodies (rods) on muscle biopsy. "Some cases of patients with TPM2 mutations presented with nemaline myopathy (NM) associated with the Escobar syndrome phenotype." (PMID 36292632, 2022). "Heterozygous pathogenic variants in TPM2 cause autosomal dominant nemaline myopathy 4 which accounts for < 1% of cases of nemaline myopathy." (PMID 33827624, 2021). "TPM2 nemaline myopathy is generally causative of a typical congenital phenotype and is commonly associated with involvement of the masticator muscles and distal lower leg muscles." (PMID 33827624, 2021). "Though almost all TPM2 gene mutations are inherited in an autosomal dominant manner, one homozygous nonsense TPM2 mutation was found in a patient with a very severe nemaline myopathy." (PMID 27726070, 2017). "Mutations in the β-tropomyosin gene (TPM2) have been shown to be associated with a spectrum of phenotypes ranging from a pure distal arthrogryposis (DA) to cap disease and nemaline myopathy." (PMID 27726070, 2017). "Skeletal muscle diseases, for example, nemaline myopathy, cap disease, and distal arthrogryposis syndromes, are associated with mutations in Tpm2." (PMID 24701242, 2014). "Pathogenic TPM2 variants are causative of several disorders, including nemaline myopathy (NM) and cap myopathy (CM), congenital fiber type disproportion (CFTD), and distal arthrogryposis (DA)." (PMID 39311120, 2024). "Congenital diseases associated with TPM2 include nemaline myopathy (NM) and cap myopathy (CM), which are both associated with extreme muscle weakness (hypotonia)." (PMID 35579956, 2022). "In order to explain the clinical heterogeneity between the two patients with TPM2 mutation, and especially for Patient 3, who was paralyzed at a young age, we investigated variants in other genes involved in nemaline myopathy (NM), akinesia/hypokinesia, arthrogryposis, and LMPS." (PMID 36292632, 2022). "Mutations in TPM2 and TPM3 encoding for β-tropomyosin (βTm) and slow α-tropomyosin (αTm-slow) are rare cause of CMs and have been associated with a number of different entities, mainly CFTD, nemaline myopathy and cap myopathy." (PMID 32456280, 2020). "Similarly, several missense mutations in TPM2 and TPM3 have been implicated in nemaline myopathy that suggest the functional importance of these genes or particular isoform in cellular function." (PMID 27703814, 2016).
colorectal cancer (13 papers, 2021 to 2025). A primary or metastatic malignant neoplasm that affects the colon or rectum. "The authors highlighted that the overexpressed BGN, RCN3, TAGLN, MYL9 and TPM2 in cancer-associated fibroblast as potential prognostic biomarkers for patients with colorectal cancers." (PMID 36172359, 2022). "The expression of CNN1 gene had previously been associated with malignant transformation and has recently been included, together with TPM2 gene expression, in a transcriptional regulatory network associated with colorectal cancer recurrence." (PMID 35454931, 2022). "TPM2, a marker of fibroblasts, was previously reported to be associated with poor prognosis in colorectal cancer (CRC)." (PMID 34771544, 2021). "TPM2 is associated with unfavorable tumor prognoses, and prior studies have confirmed its function as an oncogenic glycoprotein that promotes proliferation and metastasis in colorectal cancer." (PMID 41127012, 2025). "Some studies have shown that abnormal expression of TPM2 maybe closely associated with the development of colorectal cancer and breast cancer." (PMID 36518627, 2022). "The TAGLN, MYL9, and TPM2 were found to be over-expressed in fibroblasts from primary tumors compared to adjacent normal tissues and were associated with a poorer prognosis in the TCGA cohort of colorectal cancer." (PMID 34771544, 2021). "During liver metastasis in colorectal cancer, the expression levels of TPM2, RPS17, and TNNT1 were significantly elevated, SPINK4 expression was reduced in the epithelial cells." (PMID 41127012, 2025). "In colorectal cancer cell lines, down-regulated TPM2 has been found to enhance tumor proliferation and migration, whereas TPM2 overexpression attenuates the malignant phenotype of tumor cells." (PMID 36823643, 2023). "In colorectal cancer cell lines, the study found that TPM2 down-regulation can promote tumor proliferation and migration, whereas TPM2 over-expression attenuates the malignant phenotype of tumor cells." (PMID 37876534, 2023). "Recently, a large cohort study has identified TPM2 as a prognostic marker for colorectal cancer things." (PMID 37876534, 2023). "For example, TPM2 expression is downregulated in colorectal cancer and esophageal squamous cell carcinoma." (PMID 36823643, 2023). "More interestingly, most recent studies based on single-cell gene expression analysis in colorectal cancer surgical specimens, concur in the identification of both CNN1 and TPM2 as TASC markers associated with poor prognosis." (PMID 35454931, 2022). "BGN, RCN3, TAGLN, MYL9, and TPM2 were identified as fibroblast-specific biomarkers with a poor prognosis in colorectal cancer." (PMID 35785171, 2022). "Previous research has shown that the overexpression of Tpm2 suppresses cell proliferation and migration by regulating RhoA signaling in colorectal cancer." (PMID 33628783, 2021). "Recently, a large cohort study has identified TPM2 as a prognostic marker for colorectal cancer." (PMID 36823643, 2023). "The expression levels of TPM2, RPS17, and TNNT1 progressively increased during the progression and metastasis of colorectal cancer (CRC); in contrast, SPINK4 expression initially rose before sharply declining." (PMID 41127012, 2025). "During the metastasis process, we observed significant increases in the expression of the TPM2, RPS17, and TNNT1 genes in colorectal cancer epithelial cells, while SPINK4 expression was notably reduced." (PMID 41127012, 2025). "The expression levels of TPM2, RPS17, and TNNT1 were significantly elevated, while SPINK4 expression was reduced in the epithelial cells of colorectal cancer with liver metastasis." (PMID 41127012, 2025).
breast carcinoma (11 papers, 2012 to 2023). "TPM2 is closely related to paclitaxel resistance in breast cancer patients, with poor survival rates." (PMID 35971319, 2022). "Furthermore, we overexpressed TPM2 in breast cancer cell line MCF-7 with endogenous low expression of TPM2." (PMID 36823643, 2023). "Furthermore, the decreased expression of TPM2 promotes breast cancer metastasis and chemoresistance to paclitaxel treatment and leads to poor survival rates among breast cancer patients." (PMID 36823643, 2023). "Additionally, TPM2 is upregulated in ovarian cancer, liver cancer, and breast cancer." (PMID 35968507, 2022). "Another study demonstrated 5-aza-dC treatment induced up-regulation of TPM2 (encoding Tm1), but not TPM1, in metastatic breast cancer cells, while TPM1 and TPM2 were both up-regulated in demethylated fibrosarcoma cells." (PMID 26475688, 2015).
distal arthrogryposis (8 papers, 2015 to 2026). A muscle tissue disease characterized by congenital joint contractures of hand and feet. "As TPM2 caused distal arthrogryposis is a heterogeneous category of inherited limb malformation syndromes with substantial clinical and genetic heterogeneity and variable expressivity." (PMID 39757988, 2025). "Recently, it has also been shown of particular interest in TPM2-related myopathies and in certain forms of distal arthrogryposis such as that due to ECEL1 mutations." (PMID 36968005, 2022). "Previous studies have suggested that human mutations in TNNT3, TNNI2, and TPM2 increase the contractility of fast-twitch muscle fibers and cause distal arthrogryposis (DAs) disease." (PMID 26630129, 2015). "In contrast, pathogenic variants in homologous genes such as MYH2, TPM2, and TNNI2 that encode parts of the skeletal muscle sarcomere cause muscle diseases affecting skeletal muscle, such as distal arthrogryposis (DA) syndromes and skeletal myopathies." (PMID 37457373, 2023).
prostate carcinoma (7 papers, 2016 to 2025). A carcinoma that arises from epithelial cells of the prostate gland. "TPM2 encodes beta-tropomyosin, a member of the actin filament binding protein family that is poorly expressed in high-grade, relapsed, and metastatic prostate tumours and may be a potential prognostic biomarker in prostate cancer." (PMID 34112125, 2021). "Gain-of-function experiments demonstrated that TPM2 upregulation has a tumor suppressor effect in prostate cancer cells." (PMID 36823643, 2023). "The TPM2 gene, with high clinical relevance had been regarded as a poor prognostic biomarker in some studies, including human colon cancer, endometriosis, and prostate cancer, which supported our results." (PMID 39060620, 2024). "Tm1 subtype is one of the 2 mutants of TPM2 gene, and studies have confirmed that Tm1 is low expressed in prostate cancer, yet the exact molecular function of the genes remains unknown." (PMID 31159706, 2019). "Varisli showed that the expression of TPM2 may decrease with growing score of cancer and suggested the level of this protein are useful as a prognostic biomarker tool for prostate cancer." (PMID 27713912, 2016). "Considering the importance of androgen and AR signal in the development of prostate cancer and the progression of prostate cancer, CSS-FBS medium, which depleted androgen in the medium, was used to explore the effect of TPM2 on androgen level reactivity in PCa cells." (PMID 36823643, 2023).
arthrogryposis (6 papers, 2016 to 2023). A rare, non-progressive congenital disorder characterized by multiple joint contractures which are present at birth. "These four altered genes (TPM2, KLHL30, KLHL40, and CACNA1S), detected using WES, are expressed in the muscle and have been associated in the literature with akinesia, NM, and arthrogryposis." (PMID 36292632, 2022). "Distal arthrogryposis is a cause of syndromic TEV that is characterized by variations in genes that encode for components of the muscle contractile complex (MYH3, TPM2, TNNT3, TNNI2, and MYH8), resulting in muscle contractures." (PMID 30134936, 2018). "Pathogenic variants in Tropomyosin 2 (TPM2), which encodes a skeletal muscle–specific actin binding protein essential for sarcomere function, cause a spectrum of musculoskeletal disorders that include NM as well as cap myopathy, congenital fiber type disproportion, and distal arthrogryposis (DA)." (PMID 35579956, 2022).